FKBP5 (FKBP prolyl isomerase 5)
Diseases named in the same sentence as FKBP5 in open-access papers (continued):
Sharing a sentence is not in itself a finding about the gene and the disease.
Alzheimer disease (9 papers, 2014 to 2025). A progressive, neurodegenerative disease characterized by loss of function and death of nerve cells in several areas of the brain leading to loss of cognitive function such as memory and language. "Single-nucleotide polymorphisms (SNPs) in FKBP5 are associated with an increased risk for several psychiatric disorders, and FKBP5 has been implicated in Alzheimer’s disease (AD) by interfering with tau processing." (PMID 39227716, 2024). "Dynamic epigenetic changes across FKBP5 in the brain and association of the risk allele with brain pathology point to the possible role of FKBP5 in pathogenesis of age-dependent neurodegeneration such as Alzheimer’s disease (AD)." (PMID 35205209, 2022). "Moreover, FKBP5 expression progressively increases with normal aging, concomitant with reduced FKBP5 DNA methylation, and has been associated with the number one cause of dementia in the world, Alzheimer’s disease." (PMID 30963102, 2019). "To elucidate the contribution of rs1360780 FKBP5 C/T alleles to aging and longevity, we genotyped FKBP5 in a cohort of 800 non-demented and Alzheimer’s disease (AD) subjects of different age, taking into account the allele state of ApoE ε4, the major risk factor for AD." (PMID 35205209, 2022). "FKBP5 has been extensively investigated in the context of neurological disorders, such as post‐traumatic stress disorder (PTSD), Alzheimer's disease (AD), and Parkinson's disease (PD)." (PMID 40254776, 2025). "In a study, the FKBP5 rs1360780 and FKBP5 promoter methylation status was combined with EEG parameters in Alzheimer’s disease patients, while, in another study, EEG was used to explore the contribution of MR gene variants in habit learning under stress." (PMID 38391714, 2024). "Interestingly, FTD-Tau patients and late stage Alzheimer’s Disease patients, upregulation of several A1-specific genes (e.g., GBP2, SERPING1, FKBP5) was observed." (PMID 34158119, 2021).
lung carcinoma (9 papers, 2011 to 2025). "Activation of FKBP5 transcription via the androgen receptor (AR) was reported in prostate cancer and via the GR in human lung cancer A549 cells." (PMID 38786025, 2024). "FK506 binding protein 5 expression can also be induced by the GR in human lung cancer A549 cells, where FKBP5 mRNA are accumulated in response to dexamethasone exposure." (PMID 21119664, 2011). "However, when it comes to oxidative stress, which can connect FKBP5 to AD and PD alike, there has been few study concerning environmental toxin-induced oxidative stress in the lung cancer cell line." (PMID 40395692, 2025).
myocardial infarction (9 papers, 2018 to 2024). Gross necrosis of the myocardium, as a result of interruption of the blood supply to the area, as in coronary thrombosis. "We expected that FKBP5 genotype would be associated with depressive symptoms specifically in those CHD patients who had experienced a prior myocardial infarction (MI) or coronary revascularization entailing a more stressful CHD course." (PMID 32860562, 2020). "Here, FKBP5 was found to be one of a set of five proteins for the identification of myocardial infarction." (PMID 37681923, 2023). "For example, FKBP5 is upregulated in elderly patients with acute myocardial infarction." (PMID 32760250, 2020). "It has been demonstrated that FKBP5 may play a role in vascular endothelial function in exercise in obese individuals as well as on endothelial platelet aggregation in individuals with acute myocardial infarction." (PMID 29951131, 2018).
glioma (7 papers, 2010 to 2022). A benign or malignant brain and spinal cord tumor that arises from glial cells (astrocytes, oligodendrocytes, ependymal cells). "A study published in 2015 claimed the inhibitory and apoptotic effects of FKBP5 on the proliferation of glioma cells, suggesting its alternative roles in different cancers." (PMID 36430579, 2022). "Recent data show that celecoxib down-regulates PD-L1 via FKBP5 in murine glioma stem cells, proving a suitable adjuvant for PD-1 inhibitors as well." (PMID 33922284, 2021). "Here, we address the expression and function in glioma of FKBP51s, a protein isoform that is generated by an alternative splicing of the FKBP5 gene." (PMID 28978117, 2017). "FKBP5 is over expressed in gliomas and down regulation of FKBP5 expression using siRNAs suppresses glioma cell growth." (PMID 20423517, 2010).
pancreatic cancer (7 papers, 2011 to 2024). "We have previously shown that activated Akt signaling is associated with low levels of FKBP5 in pancreatic cancer cells." (PMID 22590527, 2012). "In the present study, we set out to comprehensively study how FKBP5 genetic polymorphisms might play a role in gemcitabine response and, ultimately, overall survival of pancreatic cancer patients." (PMID 23936393, 2013). "In our preliminary studies, we noticed that knock-down of FKBP5 expression in pancreatic cancer cells can contribute to decreased GR expression." (PMID 23936393, 2013). "We studied the role of genetic variation in FKBP5 and its effect on FKBP5 gene transcriptional regulation as well as response to gemcitabine in the treatment of pancreatic cancer." (PMID 23936393, 2013). "To identify genetic variation in the FKBP5 gene, we performed Next Generation sequencing of DNA derived from 60 pancreatic tumor and normal tissue samples obtained from pancreatic cancer patients by sequencing an area of 160 kb of DNA on chromosome 6p21." (PMID 23936393, 2013). "This comprehensive FKBP5 pharmacogenomic study provides enhanced understanding of the role of inheritance in variation in gemcitabine response in the treatment of pancreatic cancer." (PMID 23936393, 2013). "In summary, the findings presented here indicated the importance of FKBP5 in pancreatic tumor growth and chemoresistance." (PMID 22590527, 2012). "Variability in FKBP5 expression level is a major factor contributing to variation in response to chemotherapeutic agents including gemcitabine, a first line treatment for pancreatic cancer." (PMID 23936393, 2013). "In addition, when we treated pancreatic cancer cells with gemcitabine, the expression of FKBP5 as well as GR was upregulated in a dose dependent manner, even when GR expression was initially knocked-down in these cells." (PMID 23936393, 2013). "Therefore, we set out to identify genetic variation in FKBP5 by performing Next Generation resequencing of this gene in 60 tumor and normal DNA samples obtained from 43 pancreatic cancer patients treated with gemcitabine." (PMID 23936393, 2013). "Genetic variation in FKBP5 could influence its function and, ultimately, treatment response of pancreatic cancer." (PMID 23936393, 2013). "In summary, the present study provides additional evidence suggesting that SNPs in FKBP5 might contribute to gemcitabine response in the treatment of pancreatic cancer." (PMID 23936393, 2013). "Previous studies have demonstrated that FKBP5 expression is down-regulated in pancreatic cancer and have suggested that FKBP5 may be involved in the tumorigenesis of pancreatic cancer." (PMID 22590527, 2012). "The SU86 pancreatic cancer cell line was stably transfected with pooled FKBP5 shRNA." (PMID 22590527, 2012). "In the current study, we have taken a step forward by using a pancreatic cancer xenograft mice model to show that down regulation of FKBP5 in shFKBP5 xenograft mice promotes tumor growth and resistance to gemcitabine, a phenomenon consistent with our previous findings in pancreatic cell lines." (PMID 22590527, 2012). "In the current study, we tested that hypothesis by using an FKBP5 knockdown pancreatic cancer xenograft mouse model (shFKBP5) and the results of these experiments may form a foundation for future clinical translational studies." (PMID 22590527, 2012). "In addition, FKBP5 expression is low or lost in many pancreatic cancer cell lines and pancreatic cancer patient samples, correlating with increased Akt Ser473 phosphorylation." (PMID 22590527, 2012). "Since our previous studies showed that the expression level of FKBP5 was correlated with the sensitivity of pancreatic cancer cells to chemotherapeutic drugs, we next determined whether knockdown of FKBP5 could affect the chemosensitivity of SU86 xenografts to gemcitabine in vivo." (PMID 22590527, 2012).
pancreatic cancer (continued). "Moreover, the data suggest that specific Akt inhibitors might be promising adjuvant therapies for pancreatic cancer, especially in patients with lower level of FKBP5." (PMID 22590527, 2012). "Therefore, FKBP5 could be a tumor suppressor in pancreatic cancer and it could also be a biomarker for response to chemotherapy, especially gemcitabine therapy, a first line treatment for pancreatic cancer." (PMID 22590527, 2012). "We also showed that FKBP5 expression level could potentially be used as a biomarker for treatment selection of gemcitabine with or without Akt inhibitors using pancreatic cancer xenograft mice." (PMID 23936393, 2013). "Indeed, we found that FKBP5 levels were low or absent in pancreatic cancer cell lines and tissue samples from patients with pancreatic cancer, correlating with increased AKT Ser473 phosphorylation." (PMID 21119664, 2011).
Sepsis (7 papers, 2014 to 2026). Sepsis is defined as life-threatening organ dysfunction caused by a dysregulated host response to infection. "Using clinical sepsis samples and normal healthy controls, we identified the key genes associated with inflammation in sepsis, including remarkable increases in FKBP5 and SORT1 expression, as indicated through RT-PCR studies." (PMID 33959663, 2021). "Interestingly, several of the genes linked to glucocorticoid signaling (Arl4d, Cdkn1a, Ddit4, Fkbp5, Gjb6, Il6ra, Klf15, Nfkbia, Rhob, Sdc4, Sgk1, Sult1a1, Tob2, Wipf3) and apoptotic process were still upregulated 4 days post-sepsis." (PMID 31278440, 2019). "FKBP5 protein levels were markedly higher in sepsis patients than in healthy volunteers and significantly lower in survivors than in non‐survivors." (PMID 40525648, 2026). "In this study, FKBP5 expression was markedly increased in patients with sepsis and correlated with both cytokine levels and disease severity." (PMID 40525648, 2026). "Transcriptome expression profiling from GEO datasets was used to analyse RNA levels of FKBP5 in whole blood‐derived RNA from patients with sepsis and healthy controls." (PMID 40525648, 2026). "Bioinformatics analysis indicated that Fkbp5 mRNA was significantly upregulated in sepsis patients compared to controls and showed a strong association with patient survival." (PMID 40525648, 2026). "Receiver operating characteristic (ROC) curve analysis yielded an area under the curve (AUC) of 0.6941 (95% CI: 0.6332–0.7550, p < 0.0001) for FKBP5 in identifying sepsis." (PMID 40525648, 2026). "Using sepsis‐induced ARDS models in Fkbp5−/− and bone marrow chimeric mice, this study demonstrated that non‐haematopoietic FKBP5 mitigates inflammatory injury." (PMID 40525648, 2026). "FKBP5 has been shown to contribute to the regulation of myeloid-derived suppressor cells (MDSCs) and changes in MDSCs have been shown important in a sepsis model." (PMID 24612859, 2014). "Overexpression of FKBP5, as observed in our results, may play a role in promoting inflammation signaling in sepsis." (PMID 33959663, 2021). "AKT1, top up- (FKBP5, SORT1, VNN1, and CST7) and downregulated (PRR5L, SH2B3, SULF2, PLEKHO1, and PTPN6) genes in sepsis were validated using RT-PCR." (PMID 33959663, 2021). "Levels of GILZ (p = 0.018), ZFP36 (p = 0.006), FKBP5 (p = 0.012) and NRF2 (p = 0.009) mRNA were reduced, whereas CSE (p = 0.012) and HIF1α (p = 0.020) were elevated in sepsis." (PMID 32477273, 2020).
coronary artery disease (6 papers, 2020 to 2024). "In addition, FKBP5 has been reported to contribute to stress-related cardiovascular risk and metabolic disorders, for instance coronary artery disease and hepatic disease." (PMID 39702772, 2024). "The expression of FKBP5 is related to the progression of coronary artery disease." (PMID 34218797, 2021).
Borderline personality disorder (5 papers, 2016 to 2025). A personality disorder characterized by impulsive behavior and unpredictable, capricious mood. "The findings indicated that borderline personality disorder was significantly correlated with each of the five FKBP5 polymorphisms." (PMID 37051166, 2023).
Hepatic steatosis (5 papers, 2020 to 2026). Steatosis is a term used to denote lipid accumulation within hepatocytes. "HFD-induced hepatic steatosis and inflammation were prevented in FKBP5-deficient mice." (PMID 41699049, 2026). "Moreover, FKBP5 is thought to contribute to liver dysfunction and in one study, deletion of FKBP5 protected knock-out mice from fatty liver disease despite high fat diets." (PMID 36303554, 2022). "Moreover, FKBP5-knockout mice fed with an HFD are resistant to weight gain and hepatic steatosis, and have reduced adipose tissue." (PMID 33066464, 2020).
ovarian carcinoma (5 papers, 2014 to 2025). A malignant neoplasm originating from the surface ovarian epithelium. "In fetal ovaries, exposure to dexamethasone increased FKBP5, and overexpression of FKBP5 was associated with chemoresistance in ovarian cancer cells, suggesting that ovarian FKBP5 is involved in the ovarian response to xenobiotic exposure." (PMID 38666409, 2024). "In a study on an ovarian cancer cell line, the upregulation of FKBP5 increased the resistance to chemotherapeutic agents, whereas the gene silencing sensitized ovarian cancer cells to taxol." (PMID 33233407, 2020). "Our findings suggest that mitotoxin-based treatment against ovarian cancer should be avoided when the Akt/FKBP5/AR axis is activated." (PMID 25460502, 2014). "To examine the possible link between Akt and FKBP5 in ovarian cancer cells, we examined the levels of Akt kinase and found significant inhibition of Akt phosphorylation or activation (pAkt) following FKBP5 silencing." (PMID 25460502, 2014). "Since ABCB1 has been shown to represent an important factor for multiple drug resistance, the finding that the FKBP5/AR/ABCB1 axis plays a role in txr in ovarian cancer cells supports the usefulness of our strategy." (PMID 25460502, 2014). "We also found that AR binds the Akt-dependent FKBP5 immunophillin, enhancing its transactivation activity, an observation which suggests that this protein may represent a key marker of txr in ovarian cancer cells." (PMID 26318424, 2015). "Our results indicate that a normal level of FKBP5 is able to stabilize AR or lead to its accumulation in ovarian cancer as well as in non-cancer HEK293T cells." (PMID 25460502, 2014).
Parkinson disease (5 papers, 2022 to 2025). A progressive degenerative disorder of the central nervous system characterized by loss of dopamine producing neurons in the substantia nigra and the presence of Lewy bodies in the substantia nigra and locus coeruleus. "Both bisphenols affected pathways such as “PARK2/PINK1/UCHL1 in Young Onset Parkinson’s Disease”, “TNF activation of NF-kB Expression Targets”, and “Androgen Receptor/FKBP5 Signaling”." (PMID 41012393, 2025).
alcohol use disorder (4 papers, 2016 to 2025). "The FKBP5 gene is known to have an important role in alcohol use disorder (AUD) in response to stress and has been reported to affect stress responses by interacting with childhood trauma." (PMID 34531492, 2021). "FKBP5 can be used as a biomarker for the diagnosis of alcohol use disorder." (PMID 27527158, 2016). "These insights have driven the development of FKBP5 inhibitors, which are now being explored in clinical trials for PTSD and alcohol use disorder." (PMID 41234420, 2025).
COVID-19 (4 papers, 2021 to 2023). A disease caused by infection with severe acute respiratory syndrome coronavirus 2. "Interestingly, induction of FKBP5 expression among ciliated cells from severe COVID-19 participants is fully explained by corticosteroid treatment, consistent with the role for this protein in modulating glucocorticoid receptor activity." (PMID 34352228, 2021).
dyslipidemia (4 papers, 2020 to 2025). "Analyses revealed that a higher number of C alleles of FKBP5 rs1360780 was significantly associated with dyslipidemia (odds ratio [OR] = 1.69, 95% confidence interval [CI] = 1.10–2.61, p = 0.016)." (PMID 32860562, 2020). "Slc7a8, Pck1, Mgll, and Bhmt are associated with the regulation of metabolic homeostasis in the treatment of metabolic syndrome, and Fkbp5 plays a crucial role in the inflammatory response." (PMID 39126116, 2024).
trauma (4 papers, 2013 to 2022). "Also, recently several single nucleotide polymorphisms of the FK506 binding protein 5 (FKBP5) were found to interact with childhood trauma in order to create PTSD susceptibility." (PMID 27563374, 2016). "Elisabeth Binder’s team concentrated on the methylation of the FKBP5 gene, PTSD, and childhood trauma." (PMID 36458128, 2022).
viral infection (4 papers, 2019 to 2023). "Enhanced expression of FKBP5 after viral infection was confirmed by Western blot and immunohistochemical staining." (PMID 37673339, 2023). "IFNs-induced protein 44-like (IFI44L) was identified as negatively modulator for innate immune response induced by virus infection, which interacts with FKBP5 to decrease the phosphorylation of IRF-3 and NF-B mediated by IKK and IKK, respectively." (PMID 34884921, 2021). "Then, the expression of IFI44-HA, FKBP5-FLAG, actin (as a control), and the viral nucleoprotein (NP) (as a marker of viral infection) was analyzed by Western blotting." (PMID 31455651, 2019).
Cerebral ischemia (3 papers, 2020 to 2025). Restriction of arterial blood supply to the brain associated with insufficient oxygenation to support the metabolic requirements of the tissue. "Upregulation of FKBP5 in brain ischemia/reperfusion injury has been found to be associated with the severity of ischemic and reperfusion damage." (PMID 41098728, 2025). "In a previous study, Fkbp5 was upregulated in cerebral ischemia-reperfusion injury and regulated autophagy via the AKT/FOXO3 signaling pathway." (PMID 40529227, 2025). "Furthermore, using the tMCAO model to study in vivo, we determined that after cerebral ischemia, the relative expression of FKBP5 in the plasma might reflect it in brain tissues." (PMID 32760250, 2020).
chronic obstructive pulmonary disease (3 papers, 2019 to 2023). A chronic and progressive lung disorder characterized by the loss of elasticity of the bronchial tree and the air sacs, destruction of the air sacs wall, thickening of the bronchial wall, and mucous accumulation in the bronchial tree. "A recent study showed an association of the FKBP5 gene with chronic obstructive pulmonary disease (COPD), and those with a particular genetic variant respond better to inhaled corticosteroids." (PMID 32670284, 2020).
cognitive deficits (3 papers, 2019 to 2023). "Many of these psychiatric disorders present with dementia and other cognitive deficits, but a direct connection between these issues and alterations in FKBP5 remains unclear." (PMID 30963102, 2019).
dependence (3 papers, 2018 to 2024). "Almost consistently, these studies revealed that polymorphisms in COMT, BDNF, and FKBP5 genes might interact with early life stress and cannabis abuse or dependence, influencing various outcomes of schizophrenia spectrum disorders and BD." (PMID 28822116, 2018). "Magi2 polymorphisms may also influence nicotine dependence in smokers; and 6) FK506 binding protein 5 (Fkbp5) which has been linked to DNAm changes in blood as discussed, but also modulates the effects of nicotine on the hypothalamic pituitary adrenal axis in female smokers." (PMID 38436597, 2024).